IL7 (interleukin 7)
Diseases named in the same sentence as IL7 in open-access papers (continued):
Sharing a sentence is not in itself a finding about the gene and the disease.
tumor (continued). "The lack of correlation with tumor size, lymph node metastasis, and all other histopathological characteristics of the tumor, maybe due to the production of IL-7 by immune system cells and not by tumor cells, questions its use as a prognostic indicator." (PMID 35794603, 2022). "In one study that highlighted this immune-regulation potential, Glycyrrhiza polysaccharide was fed to CT-26 tumor-bearing mice and significantly inhibited tumor growth, increased the immune organ index, activated CD4+ and CD8+ immune cells, and increased levels of IL-2, IL-6, and IL-7 cytokines." (PMID 36090181, 2022). "As the expansion and persistence of CAR T cells correlate with clinical response, we reasoned that interleukin-7 (IL-7), a pro-lymphoid growth and survival factor involved in the development, maintenance, and proliferation of T cells, would promote CAR T cell efficacy and tumor cell killing in vivo." (PMID 35697686, 2022). "Oncolytic adenovirus that was loaded with IL-7 combined with B7H3-targeted CAR-T therapy enhanced T-cell proliferation, increased tumor-infiltrating B7H3-CAR-T-cells, and extended the survival of mice bearing GL161 tumours, despite failing to reverse the exhaustion of B7H3-CAR-T-cells." (PMID 36145510, 2022). "Similarly, IL-7 stimulation did not affect the percentage of tissue-infiltrating CD8+ T cells expressing mCD127 in either tumor or para-tumor tissues (P > 0.05)." (PMID 35850640, 2022). "This might be due to the decreased responsiveness of CD8+ T cells to IL-7 in cancers, As previous findings showed that IL-7 did not affect tumor patients derived CD8+ T cell proliferation in vitro." (PMID 35850640, 2022). "Furthermore, CTL that does not express IL-7Rα can be modified by gene editing to restore the response to IL-7, promote the cell proliferation, and have anti-tumor activity without significantly changing their antigen dependence and specificity." (PMID 36142322, 2022). "Importantly, IL-7 secretion in the presence and absence of tumor cells, was also detected as a distinct feature of 28z/IL-7 CAR-T cells using the multiplexed cytokine assay." (PMID 35869100, 2022). "The administration of IL-7 has been found to significantly boost mouse anti-cynomolgus-monkey anti-simian immunodeficiency virus (SIV) infection, mouse anti-4T1 breast tumor invasion, lymphocytic choriomeningitis virus (LCMV) infection, and mouse anti-E.G7-OVA tumor invasion." (PMID 34956167, 2021). "Consequently, self-tumor Ag-specific CD8+ T cells have a higher chance of being activated and proliferated under lymphopenic rather than non-lymphopenic conditions, which can be further enhanced by IL7-Fc." (PMID 34440787, 2021). "Interestingly, the transfer of IL-7/CCL19-producing CAR T cells resulted in an increase in both CAR T cells and non-CAR T cells within the tumours, suggesting that IL-7 secretion also confers a bystander effect." (PMID 34885108, 2021). "Interestingly, IL-5, IL-7, IL-20, and IL-22, rather than their receptors, have been widely reported to have the ability to predict tumor prognosis." (PMID 34497605, 2021). "Collectively, our data suggest that IL7-Fc preferentially enhances the antitumor effect of CD8+ T cells only under lymphopenic conditions, which might be due to the temporal rescue of tolerant self-tumor Ag-specific CD8+ T cells from peripheral tolerance." (PMID 34440787, 2021). "In a xenograft model, CAR T cells efficiently suppressed tumor growth in the presence of non-modified MSCs that could only slightly be improved in the presence of IL7/IL12 engineered MSCs." (PMID 32260097, 2020). "Stromal cells can mediate immune-suppression and protect tumor cells from cytotoxicity via secretion of soluble factors including immune suppressive mediators such as IL-10, TGF-β and PGE2 or growth factors such as stem cell factor (SCF), IL-7, IL-15, CXCL-12 among others." (PMID 32483120, 2020).
tumor (continued). "After 7 days of co-cultured with tumor cells, NKG2DIL7-CAR T cells exhibited lower expression of PD-1 and Tim-3, especially in Tim3+ PD1+ expression, suggesting that IL-7 could prevent CAR-T cell exhaustion and protect T cells from deleterious immunosuppressive actions of tumor cells." (PMID 32698361, 2020). "We next crossed Il7-Cre mice with Cxcl12fl/fl mice and found that cell type-specific genetic ablation of Cxcl12 expression substantially reduced the frequency of tumor-initiating cells (1 in 4,809 control vs. 1 in 44,814 Il7-Cre Cxcl12fl/fl) without affecting the time to engraftment." (PMID 29632733, 2018). "Of note, only 1 of the 5 mice in the IL-2 group was cured of tumor (no visible tumor 42 days after injection), whereas in the IL/15/21 group, four of the five mice were cured and all five mice were cured of tumor in the IL-21, IL-2/21 and IL-7/15 groups." (PMID 28146052, 2017). "However, in mice, CD8 αβ T cells expanded ex vivo using IL-15 or IL-7/IL-15 rather than IL-2, mediate increased tumor immunity." (PMID 28239463, 2017). "Additionally, depletion of endogenous IL-7 in the host did not abrogate the capacity of CAL-101-primed T cells to clear tumor." (PMID 29033940, 2017). "Considering both IL-7 and IFN-γ signalling in host cells are required for combination therapy-induced tumour rejection, a process dependent on T cells, we speculated that IL-7 and IFN-γ signalling in T cells dictate the immunotherapeutic benefits of combination therapy." (PMID 27498556, 2016). "There is no data demonstrating the exact cell source of IL-7 detected in tumor sample." (PMID 25955647, 2015). "Based on the results of the tumor challenge and growth, it was concluded that PAP-specific immune activation occurred in the mice treated with the PAP-fused cytokines, and the antitumor effects were significantly enhanced by the additional cytokine (IL2, IL4 and IL7) fusion proteins." (PMID 25632844, 2015). "The anti-tumor activity of combining IL-7 and chemotherapy has not been studied." (PMID 24465710, 2014). "TSLP, a cytokine structurally related to IL-7, is produced by a variety of cell types and influences a diverse range of target cells, including immune cells like B cells, T cells, DCs, eosinophils, and NK cells, as well as non-immune cells such as smooth muscle and tumor cells." (PMID 40724851, 2025). "Similarly, macrophages in metastatic UVM showed strong enrichment for cytokines like Adiponectin, Prolactin, IL7, IL10, IL15, IL9, IL31, APRIL, Persephin, and IL22, highlighting their role in creating a pro-tumorigenic environment through immune modulation and support of tumor growth." (PMID 39916959, 2024). "Although IL-7 was known to promote the T-ALL proliferation and mutational activation of IL-7Rα was reported to promote the development of T-ALL, we did not observe increased tumor burden or decreased survival with rhIL-7-hyFc treatment alone in either CTCL or T-ALL PDX models." (PMID 37798328, 2023). "With in-depth analysis, we found that IL-7 maintained CAR-T cells in a less differentiated T-cell state, regulated distinct metabolic activity, and prevented CAR-T-cell exhaustion, which could be essential for CAR-T cells to maintain their metabolic fitness and anti-tumor response." (PMID 35869100, 2022). "Therefore, we conclude that IL7-Fc should be temporally administered to cancer patients under lymphopenic conditions to avoid the excessive expansion of CD8+ T cells that do not target tumor antigens." (PMID 34440787, 2021). "In addition to IL-12 and IL-18, CAR T cells engineered to secrete IL-7, IL-15, and IL-21 (covered in more detail in the next section), although primarily intended to enhance the persistence and activity of the CAR T cells themselves, will also stimulate anti-tumour responses in bystander cells." (PMID 34885108, 2021).
tumor (continued). "The combination of DDP and TCM could restore the IL-7/IL-7R signals in TCM dose-dependent manner, suggesting that DDP impaired the protective role of IL-7 during the chemotherapy but the TCM could inhibit this effect and recover the IL-7/IL7R expressions in tumor tissues." (PMID 31138762, 2019). "Lastly, many T cell stimulatory cytokines including IL-2, IL-7, and IL-15 play an important role in enhancing anti-tumor immunity, but whether or not these cytokines render T cells resistant to the suppressive effects of Treg cells in the context of anti-tumor immunity is unclear." (PMID 31058083, 2019). "In regards to the ex vivo expansion setting, we could not distinguish any superiority in terms of anti-tumor activity in vivo among IL-7, IL-15, IL-18, IL-21 and no cytokine (NC) conditions, perhaps due to CART cell number being sufficient to eliminate tumor in all the groups." (PMID 27409425, 2016). "Moreover, studies have shown that, in the highly dynamic tumor-immune system, the expression of PD-L1 in tumor microenvironment can also be induced by CD8-positive T cells, as well as cytokines such as interferon γ, IL-2, IL-7, IL-15, and IL-21 in a positive feedback mechanism." (PMID 27120796, 2016). "The lack of efficacy in this model was likely due to the absence of significant tumor immune infiltrates (CD4+ and CD8+ T cells) in the Ad.IL-7/B7.1 treatment group compared to the control group." (PMID 40957993, 2025). "Early phase clinical trials of dual IL-7 and CCL19-armored CAR T-cell have reported preliminary evidence of anti-tumor activity and no grade >2 toxicities, although further studies will be needed to confirm clinical benefit." (PMID 41019052, 2025). "In summary, an autologous tumor cell vaccine loaded with a non-lytic NDV expressing IL-7 (i.e., LX/IL-7) provides significant prophylactic and therapeutic benefits by activating tumor-specific cytotoxic T-cell responses." (PMID 40957993, 2025). "Future studies should explore the use of a lytic NDV strain expressing IL-7 and evaluate its efficacy in parallel with the non-lytic NDV strain expressing IL-7, with or without being loaded into autologous tumor cells." (PMID 40957993, 2025). "We previously reported NECTIN-4 CAR-T cells co-expressing IL-7 and CCL-19 displayed significant anti-tumor activity in vitro and in vivo without obvious on-target off-tumor toxicities." (PMID 39735536, 2024). "Three of eleven LLC tumor model mice achieved complete regression (CR) in the combination group compared to none in the other groups (PBS, IL-7 or IL-12 alone)." (PMID 38753073, 2024). "We also show that IL-7–CBD and CBD–IL-12 activate nonredundant immunological pathways, with IL-7–CBD providing the memory and survival signals and CBD–IL-12 supporting the effector programs of the tumor-resident T cells." (PMID 38019919, 2023). "IL-7–CBD prevented the conversion of activated T cells into exhausted ones, resulting in functional, long-term immune memory as evidenced by the lack of tumor recurrence." (PMID 38019919, 2023). "IL-7 secretion and CCR2b expression did not affect the expression of CAR on the T cell surface and the specificity and effectiveness of CAR-T against tumor cells." (PMID 34778046, 2021). "We report that compared with that of CAR-T cells, 7×2b CAR-T cell IL-7 secretion and CCR2b expression did not affect the T cell surface expression of CAR or CAR-T specificity and efficacy against tumor cells." (PMID 34778046, 2021). "In the present study, there was no major difference in IL-7 production between NKG2D-CAR and NKG2DIL7-CAR T cells in the absence of tumor, but when co-cultured with PC-3 cells, IL-7 expression in NKG2DIL7-CAR-transduced T cells increased vigorously." (PMID 32698361, 2020). "MSCs releasing IL7 and IL12 were superior over non-modified MSCs in supporting the CAR T cell response and improved the anti-tumor attack in a transplant tumor model." (PMID 32260097, 2020).
tumor (continued). "The effect is due to MSC released IL7 and IL12 since non-modified MSCs had no impact on the anti-tumor activity of CAR T cells." (PMID 32260097, 2020). "Tumors in mice receiving IL-7, IL-15, IL-18, IL-21, and NC exposed CART cells regressed or even disappeared, without any statistical difference in tumor size at the end point." (PMID 27409425, 2016). "In contrast, IL-2, IL-7 and IL-15 induced p-STAT5 in tumor-infiltrating T cells were not different from normal T cells." (PMID 23072591, 2012). "In the syngeneic CT26 mouse model, the addition of IL-7 and IFN-α mRNA did not further enhance the IL-12 mRNA-induced anti-tumor efficacy, which may be due to the saturated levels of cytokine mRNAs in the high dose (30 μg/mouse/injection)." (PMID 39290693, 2024). "The anti-tumor efficacies of IL-12/IL-7 and IL-12/IFN-α cytokine mRNA doublets and equiquantity triplet (1:1:1 of IL-12/IL-7/IFN-α) were not significantly different from that of the IL-12 mRNA monotherapy, as evidenced by their comparable TGI indexes and median survival times." (PMID 39290693, 2024). "Finally, ex vivo culture of CAR T cells in IL-7 and IL-15 rather than traditional IL-2 is also known to favour the central memory (TCM) phenotype and increase tumour control." (PMID 37291434, 2023). "However, under non-lymphopenic conditions, IL7-Fc promotes the homeostatic proliferation of naïve CD8+ T cells, but restricts the proliferation of activated CD8+ T cells and eventually promotes tumor growth." (PMID 34440787, 2021). "However, when absolute concentrations were compared, the highest IL-7 concentrations were in CRC, both when tumor and noncancerous tissue were analyzed." (PMID 31185636, 2019). "IL7 is expressed in CS2 but not in CS1, again suggesting that CS2 may be a more conducive microenvironment for tumor growth than CS1." (PMID 23762861, 2013). "CARζ/CPR41BB cells (n = 6 donors) expanded comparably in media containing IL-7 and IL-15 (P = not significant; two-way ANOVA with the Tukey test) and exhibited proliferative capacity similar to that of second-generation CART (n = 3 donors) when exposed to HER2+/PD-L1+ tumor cells for 72 hours." (PMID 39973814, 2025). "Evaluating the phenotypic composition of the CD8+ T cells infiltrating tumor, we observed that at 48-hours after ALT administration, the endogenous CD8+ T cell phenotypes in tumors were similar, regardless of whether ALT was expanded with IL-2 or IL-7." (PMID 40244705, 2025). "Indeed, we observed that the CD8 + 28z/IL-7-CAR-T cell numbers were maintained at a stable level, but 28z-CAR-T cells were detected as 80% CD8 + T cells at the end of their lifetime in culture but no efficacy to eliminate tumor cells." (PMID 35869100, 2022). "When cervical lymph nodes (which were employed as non-tumor draining lymph nodes (non-TDLNs)), inguinal TDLNs, and spleens were analyzed on day 19, the percentages of transferred pmel-1 CD8+ T cells were minimally increased by rhIL-2 and were increased by IL7-Fc in non-TDLN, TDLN, and spleen." (PMID 34440787, 2021). "Moreover, we found that IL-7 combined with IL-12 did not increase the proportion of exhausted CD8+ T cells, despite T cell activation, in which IL-7 is assumed to contribute to maintaining T cells in the tumor microenvironment." (PMID 33909103, 2021). "Likewise, when the flank tumor was allowed to grow for 7 days rather than 4 days prior to AIT treatment, the IL-2, IL-21, IL-2/21, IL-7/15 and IL-7/15/21 groups all had significant slowing of tumor growth or tumor regression when compared to the control or cyclophosphamide-alone groups (p < 0.03)." (PMID 28146052, 2017). "CAR‐T cells in this model, it is not necessarily due to the presence of IL‐7 and/or CCL19 since 7 × 19 CAR‐T cells could produce a comparable or even higher IFN‐γ when 7 × 19 CAR‐T cells generated from a different donor were co‐cultured with a different tumor (data not shown)." (PMID 37031457, 2023).
tumor (continued). "However, gastric MAIT cells displayed considerably less de-granulation than colon- or tumor-derived MAIT cells in the current study, but this may be due to their physical location, the different bacteria used to trigger degranulation, or the lack of IL-7 priming of the gastric MAIT cells." (PMID 31073372, 2019).
cancer (206 papers, 2006 to 2026). A tumor composed of atypical neoplastic, often pleomorphic cells that invade other tissues. "For example, mRNA encoding IL2RG, the gamma subunit common to the IL-2, IL-4, IL-7 and IL-21 receptors, is overexpressed by 155% in platelet-educated cancer cells." (PMID 40096084, 2025). "The association between IL-7 and cancer cachexia highlights the potential for targeted therapies to mitigate the effects of cachexia in cancer patients." (PMID 38675377, 2024). "Further analysis confirmed that only IL-7 was associated with cancer progression, accounting for 2.63%." (PMID 32381120, 2020). "IL7R and IL7 are highly expressed in PCa and are associated cancer cell invasion and migration probably by activating the AKT/NF-κB pathway and upregulating MMP-3 and MMP-7 expression." (PMID 32704070, 2020). "An NDV variant encoding both IL-15 and IL-7 developed as a cancer vaccine conferred delayed outgrowth of B16 tumors." (PMID 31623390, 2019). "In fact, contradicting a beneficial role attributed to the cytokine, several reports have demonstrated IL-7 overexpression and oversecretion in cancer, and have linked it with unfavorable characteristics." (PMID 31185636, 2019). "Of great importance, is the ability of the polysaccharides to up-regulate anticancer cytokine IL-7, which is important in proliferation and maturation of immune cells and it is associated with better prognosis in cancer." (PMID 27401917, 2016). "Additionally, IL-7 has been associated with dysregulated energy metabolism, leading to malnutrition in cancer patients." (PMID 38675377, 2024). "Additionally, the association between higher IL-7 levels and advanced disease stages in EC suggests a prognostic role for this cytokine, similar to its role in other cancers." (PMID 39334861, 2024). "IL-7 has been shown to be associated with the development of cancers in some studies." (PMID 31915416, 2019). "This notion has resulted in considering IL-7 as a diagnostic or prognostic factor in this cancer." (PMID 24551818, 2014). "Various viruses engineered to express IL-7 have now been tested in several preclinical cancer models, demonstrating superior antitumor immunity via activation of TILs—a hallmark of “immunologically hot” tumors —compared to non-IL7-expressing viruses." (PMID 40957993, 2025). "Among various cytokines considered for cancer immunotherapy, interleukin-7 (IL-7) stands out due to its important role in T cell development, survival, and function." (PMID 40589567, 2025). "IL-7 has immunomodulatory properties that can facilitate T cell activation and promote cancer immunotherapy." (PMID 40957993, 2025). "Further studies of virally encoded IL-7 expression alone and in combination merit further investigation as a strategy for realizing the potential therapeutic value of IL-7 for cancer treatment." (PMID 40957993, 2025). "Immunotherapy with IL-7/IL-7 receptor (IL-7R) has high efficacy in a wide range of malignant tumours and has been demonstrated in animal models and in humans." (PMID 40165301, 2025). "Despite the clinical benefits of IL-7 in various therapeutic areas, including cancer, the development of IL-7 as a commercial drug is limited by its short half-life." (PMID 40490502, 2025). "Cytokines from the common gamma chain receptor family, such as IL-15, IL-21 and IL-7, show promise for cancer immunotherapy and have been incorporated individually into the immunocytokine approach." (PMID 40370435, 2025). "IL-7 is essential for the development, maintenance, and proliferation of T lymphocytes, highlighting its potential role as an adjuvant in cancer vaccine development." (PMID 41179658, 2025). "It is worth mentioning that IL-7 is a subject of interest among researchers, with its use as an adjuvant in the development of anti-cancer and anti-HIV vaccines." (PMID 41305439, 2025).